TNF (tumor necrosis factor)
Diseases named in the same sentence as TNF in open-access papers (continued):
Sharing a sentence is not in itself a finding about the gene and the disease.
diabetic retinopathy (continued). "Nb-TV can simultaneously target TNF-α and VEGF-A, effectively ameliorate vascular hyperplasia and inflammation, thereby exerting a potent therapeutic effect on diabetic retinopathy." (PMID 41567638, 2025). "Multiple cytokines and chemokines, such as IL-1β, IL-6, IL-8, TNF-α, and MCP-1, were found to be increased in serum and vitreous of the patients with diabetic retinopathy and DME." (PMID 40564027, 2025). "Pro-inflammatory cytokines and chemokines, like interleukin (IL-1ß, IL-6) interferon-γ (INF-γ), tumor necrosis factor-α (TNF-α), and intracellular adhesion molecules (ICAM) are the raised inflammatory markers in diabetic retinopathy patients." (PMID 40255802, 2025). "In diabetic retinopathy, the NLRP3 inhibitor verapamil can significantly inhibit TLR4-mediated NLRP3 activation, reduce IL-1β and TNF-α levels and improve RGC survival." (PMID 39736512, 2024). "Sesamin administration reduced levels of tumor necrosis factor-α (TNF-α) and intercellular adhesion molecule-1 (ICAM-1) and suppressed inducible nitric oxide synthase (iNOS) expression in a mouse model of diabetic retinopathy." (PMID 38337729, 2024). "In diabetic retinopathy, METTL3 upregulation was detected in pericytes treated with inflammatory stimuli, such as tumor necrosis factor-α (TNF-α), and interleukin-6 (IL-6)." (PMID 36291060, 2022). "Curcumin, the main component of turmeric, was capable to slow down inflammation in AMD, diabetic retinopathy or RP through the downregulation of IL6, TNFα, etc.." (PMID 35387197, 2022). "Macrophages along with leukocytes produce free radicals, TNF-α, and VEGF which in fact creates a vicious cycle and worsens diabetic retinopathy." (PMID 34804425, 2021). "Similar to TNF-α, it was reported that there was a significant relationship between vitreous MCP-1 level and the severity of diabetic retinopathy." (PMID 34804425, 2021). "Molecules such as interleukins, TNF, VEGF, and b-FGF are important components of the pathophysiology of diabetic retinopathy and have been extensively studied to determine their functions in this disease." (PMID 34907265, 2021). "Diabetic retinopathy is treated by regulating the AGE-RAGE signal pathway in diabetic complications, TNF signal pathway, HIF-1 signal pathway, and VEGF signal pathway." (PMID 32963574, 2020). "The target of the Compound-Xueshuantong Capsule in diabetic retinopathy treatment is significantly enriched in the AGE-RAGE signal pathway, TNF signal pathway, HIF-1 signal pathway, and VEGF signal pathway in diabetic complications." (PMID 32963574, 2020). "In diabetic retinopathy, the expression of IGFBP-3 is markedly reduced due to elevated levels of TNF-α." (PMID 31500224, 2019). "TNF-α can indeed damage the RPE cell layer, affecting the integrity of outer blood retinal barrier, that is strongly affected in diabetic retinopathy." (PMID 30013474, 2018). "In diabetic retinopathy, the expression of proinflammatory IL6 and TNF-α were significantly inhibited after decreasing the expression of HIF-1." (PMID 30662576, 2018). "Since TNFα and IGFBP-3 are key mediators of retinal damage and protection respectively in diabetic retinopathy, increased understanding of the relationship between these two proteins will offer new therapeutic options for treatment." (PMID 25073020, 2014). "The mRNA expression for pro-inflammatory cytokines such as IL-1 and Tumor Necrosis Factor Alpha (TNF-α) is increased in the retina and animal studies suggest that inhibition of TNF-α has beneficial effects in prevention of diabetic retinopathy." (PMID 18575614, 2008). "In diabetic retinopathy, phosphorylation of PI3K induces phosphorylation of AKT and mTOR, leading to increased expression of VEGF and the secretion of tumor necrosis factor-alpha (TNF-α) and IL-1, which accelerates the progression of diabetic retinopathy." (PMID 39595579, 2024).
diabetic retinopathy (continued). "As a result, in support of the literature, anti-TNF medication seems to reduce the incidence of diabetic retinopathy independent of its glucose-lowering effect." (PMID 38842591, 2024). "Inhibition of TNFα release, along with inhibition of VEGF signaling in diabetic retinopathy, has already been described in diabetic rats treated with intravitreal injection of aflibercept, likely involving the extracellular signal-regulated kinase (ERK) pathway." (PMID 33922399, 2021). "Of note, it has been shown that TNF-α knockout mice failed to develop diabetic retinopathy, indicating a major role of this inflammatory mediator in this disease." (PMID 31500224, 2019). "Another desirable characteristic of NSAIDs is tumor necrosis factor (TNF)-alpha suppression, which may inhibit early diabetic retinopathy progression." (PMID 29392145, 2017). "In addition to that, NXT reduces the development of diabetic retinopathy involved in inhibition of the expression of CAS-3, MMP-2/9, and TNF-α." (PMID 27668004, 2016). "Both TNFα and VEGF play an important role in the pathogenesis of diabetic retinopathy." (PMID 23365614, 2013). "For example, in T1DM subjects with nonproliferative diabetic retinopathy, TNF-α has been reported to be higher than the level seen in subjects without diabetic retinopathy." (PMID 23316106, 2012). "In their study, the decreased TNF-α and IL-6 levels were observed in the subjects with nonproliferative diabetic retinopathy, whilst the presence of proliferative diabetic retinopathy was associated with the increased TNF-α and IL-6 levels." (PMID 23316106, 2012). "In addition, at the early stage of diabetic retinopathy, there is no significant increase in TNF-α or IL-1β levels compared to the CON group." (PMID 41317244, 2025). "Additionally, inflammatory cytokines (TNF-α, IL-1β, and IL-6) produced by CD68-expressing macrophages recruit inflammatory immune cells in the retinas of diabetic animals, crucially contributing to the development and progression of diabetic retinopathy." (PMID 36362313, 2022). "In support of this hypothesis, TNFα knockout mice failed to develop diabetic retinopathy even when treated with a high galactose diet known to trigger manifestations of the disease." (PMID 25073020, 2014). "The suggestion of inhibition of TNFα as a therapeutic for diabetic retinopathy is not novel." (PMID 25138272, 2014). "The mechanism of TNF-α contribution to diabetic retinopathy is not fully elucidated." (PMID 17641733, 2007). "Importantly, diabetic Cd40−/− mice are protected from retinal upregulation of intercellular adhesion molecule 1 (ICAM-1), TNF-α, IL-1β, nitric oxide synthase 2 (NOS2) and C-C motif chemokine ligand 2 (CCL2) and do not develop diabetic retinopathy." (PMID 35920844, 2022).
neuropathy (132 papers, 2008 to 2026). A disorder affecting the nervous system that manifests with pain, tingling, numbness, and/or muscle weakness. "Given the increased risk of neuropathy in patients with RA treated with TNF-α inhibitors, routine neurological assessment is recommended." (PMID 41523451, 2025). "Administration of DRP1 inhibitors resulted in decreased HIV-associated neuropathy as well as TNF-induced mechanical hyperalgesia in rats." (PMID 38673830, 2024). "Nerve damage from either trauma, surgery, or neuropathies can result in neuropathic pain, which has been linked to pro-inflammatory states, mediated by bradykinin, interleukins 1,6, and 8, along with tumor necrosis factor (TNF) and C-reactive protein." (PMID 39286807, 2024). "The aims of this study were to demonstrate the presence and find risk factors of peripheral (somatic and autonomic) neuropathy patients with severe CD on anti-TNFα biological therapy." (PMID 37967139, 2023). "The proposed pathogeneses of TNF-alpha-associated neuropathies include both a T cell and humoral immune attack against peripheral nerve myelin, vasculitis-induced nerve ischemia, or inhibition of signalling support for axons." (PMID 23573450, 2013). "The proposed pathogenesis of TNF-α-associated neuropathies includes both T-cell and humoral immune attack against peripheral nerve myelin, vasculitis-induced nerve ischemia, and inhibition of signaling support for axons." (PMID 23469058, 2013). "Inflammation after neuropathy induces macrophages to activate and migrate to nerves and dorsal root ganglia, causing pain hypersensitivity through the release of pro‐inflammatory cytokines (e.g., TNF‐α)." (PMID 39749638, 2025). "Considering that peripheral nerve regeneration and neuropathies in general are associated with an inflammatory environment, we next aimed to evaluate the influence of the pro-inflammatory cytokine TNF-α on Schwann cell behavior, as well as lymphatic network development." (PMID 35740945, 2022). "Furthermore, increased TNF-α actions cause neuropathic pain in models of nerve injury or neuropathy." (PMID 23672639, 2013). "In case of the associated neuropathy of tumor necrosis factor alpha antagonists, the possible mechanisms of action include both T-cell and humoral immune attack against peripheral nerve myelin, vasculitis-induced nerve ischemia, and inhibition of signaling support for axons." (PMID 20977708, 2010). "Moreover, to confirm the efficacy of PEA formulations post-intestinal transit in eliciting a peripheral recuperative impact, an examination was conducted on one of the major inflammatory markers associated with neuropathy, namely tumour necrosis factor α (TNFα)." (PMID 39201765, 2024). "Demyelinating neurological diseases are important contraindications to initiating anti-tumor necrosis factor (TNF) biologic therapy; however, these agents can also rarely induce demyelinating conditions, including neuropathies." (PMID 41658656, 2026). "The anti-hyperalgesic effect of hesperidin in the CCI neuropathy model in rats is attributed to the inhibition of pro-inflammatory cytokines TNF-α and IL-6." (PMID 40718454, 2025). "We found ADMA and TNFα levels significantly higher in patients with neuropathy compared to controls." (PMID 40002851, 2025). "When TNF-α inhibitor-induced neuropathy is suspected, clinicians should consider discontinuing the drug and administering IVIg for persistent symptoms." (PMID 41523451, 2025). "In neuropathies, immune-cell accumulation leads to the release of inflammatory cytokines; serum TNF and IL-6 expression increase during this process." (PMID 41462977, 2025).
neuropathy (continued). "MO-administered neuropathy models of rats also showed reduced levels of serum IL-6, IL-1β, and TNF-α and reduced oxidative stress." (PMID 40297338, 2025). "Etanercept, an inhibitor of tumor necrosis factor-alpha (TNF-α), is being explored for its ability to alleviate neuropathic pain by reducing neuroinflammation, a key factor in the development and persistence of neuropathy." (PMID 39595909, 2024). "TNF-α levels correlated positively with Neuropathy Disability Scores (NDSs; ρ = 0.796, p < 0.001) and Neuropathy Symptom Scores (NSSs; ρ = 0.489, p < 0.001)." (PMID 39408723, 2024). "In the brain, the rising level of TNF-α aids the trypanosome to cross the blood-brain barrier leading to acute neuropathy." (PMID 38620045, 2024). "In this study, palmatine was observed to inhibit TNF-induced mechanical hyperalgesia, which is consistent with previous studies showing that palmatine antagonized TNF-α and IL-1β in neuropathy models." (PMID 39458972, 2024). "Further, patients with bortezomib therapy-induced neuropathy showed higher serum levels of TNF in contrast to controls." (PMID 36604634, 2023). "TNF-α is a pro-inflammatory cytokine whose involvement in neuropathy is more obvious than those of IL-6 or C-reactive protein." (PMID 37629665, 2023). "For instance, the CB2 agonist MDA7 prevented mechanical hyperalgesia and reduced the expression of TNF, IL-1β, and IL-6 in the spinal cords of mice with neuropathy induced by paclitaxel." (PMID 37891972, 2023). "Inflammatory mediators, such as TNF-α, IL-1, and IL-6, were shown in clinical and experimental research to contribute to neuropathy progression and maintenance." (PMID 37107178, 2023). "Treatment with IL-10 or TNF-α, IL-1, and IL-6 receptor antagonists substantially mitigates allodynia and hyperalgesia in neuropathy animal models." (PMID 37107178, 2023). "For instance, it was found that transgenic activation of the proinflammatory cytokine tumor necrosis factor (TNF) sourced from astrocytes aggravates mechanical hypersensitivity in a mouse neuropathy model." (PMID 37582709, 2023). "Disruption of these cells occurs in response to a variety of clinical circumstances, including exposure to inflammatory factors such as TNF and can lead to myelin breakdown and neuropathy." (PMID 36159399, 2022). "These time points of analysis allow us to evaluate the fluctuation of TNFα that has been taken into consideration as a response to neuropathy, treatment and sex, in combination or alone." (PMID 36498830, 2022). "We used TNF to induce neuropathy in the sciatic nerves of rats in vivo following treatment of either CM or ASCs to observe the regeneration capacity of each treatment." (PMID 36159399, 2022). "Since peripheral nerve injuries and neuropathies are accompanied by inflammation, we aimed to assess the influence of the pro-inflammatory cytokine TNF-α on lymphatic network formation, as well as on SC behavior." (PMID 35740945, 2022). "Previous studies reported that in the CCI-induced neuropathy model, the TNF-α, IL-1β signals, and infiltration of CD68+ inflammatory cells induced a partial decrease after nerve release." (PMID 35893792, 2022). "Specifically, these DEGs were associated with neuropathy-related pathways, such as GABRD, GABRP, TBX1, and SOX10, and inflammatory responses such as CXCL3, CXCL12, TNF, and IL6." (PMID 36147849, 2022). "They both activate glial and immune cells to release proinflammatory cytokines such as TNF-α, IL-1β, IFN-γ, and IL-6, and chemokines such CCL2 and CCL5, which cause neuronal hyperexcitability, neurodegeneration, neuropathies including neuropathic pain." (PMID 35095888, 2021). "Microglia are activated by neurotransmitters secreted from the terminals of presynaptic neurons in the dorsal horn of the spinal cord, and neuropathy is induced by the secretion of various inflammatory factors (TNF-α, IL-1β, and IL-6)." (PMID 34073390, 2021).
neuropathy (continued). "In the mouse model, the elevated expression of genes encoding TNF-α and TGF-β1 factors were demonstrated in the dorsal root ganglia (DRG) after induction of neuropathy with BTZ." (PMID 34640602, 2021). "In animals, proinflammatory cytokines IL-1α, IL-1β, and TNF-α are known contributors to the pathogenesis of neuropathy." (PMID 32908447, 2020). "In other studies, TNF-α has also been shown to be increased in patients with microvascular complications (microalbuminuria 30%, neuropathy 17.1%, retinopathy 12.9%)." (PMID 33202729, 2020). "Inflammation and neuropathy exhibit similar increases in glutamatergic signaling and gliosis in the dorsal horn, immune cell invasion, and elevations of TNF-α in the DRG thought to sensitize nociceptive signaling." (PMID 31258480, 2019). "Melatonin attenuates pain hypersensitivity by inhibition of TNF-α in oxaliplatin-induced neuropathy." (PMID 31765435, 2019). "The CCI-induced neuropathy has also been associated with significant inflammation as assessed by marked increase in MPO and TNF-α levels." (PMID 28103857, 2017). "On the other hand, inhibition of TNF in inflammatory peripheral diseases induced CNS side effects including demyelination and neuropathies, suggesting a positive role for TNF maintaining the homeostasis in the CNS." (PMID 27012931, 2016). "We previously reported that intrathecal (i.t.)injections of TGF-β1 significantly inhibit neuropathy-induced thermal hyperalgesia, spinal microglia and astrocyte activation, as well as upregulation of tumor necrosis factor-α." (PMID 27541934, 2016). "It quickly became clear that pro-inflammatory cytokines were actively contributing to chemotherapy-induced neuropathic symptoms as blockade via cytokine antagonists such as IL-1 receptor antagonist or anti-TNF-α attenuated chemotherapy-induced neuropathy." (PMID 25954147, 2015). "Others have shown that thalidomide, a biological agent shown to inhibit TNF-α, reduced chemotherapy and bone cancer induced neuropathy in rodent models." (PMID 25954147, 2015). "In HIV-1-negative individuals with painful- compared to painless neuropathies, higher blood mRNA levels of tumour necrosis factor-alpha (TNFα) and interleukin (IL)-2 have been reported." (PMID 24512313, 2014). "Elevated serum concentration of TNF-α shows a positive correlation with neuropathy severity in patients with Guillain-Barré syndrome." (PMID 23304492, 2012). "Clinicians should suspect TNF-α inhibitor-induced neuropathy when demyelination is detected." (PMID 41523451, 2025). "TNF-α, IL-1β, and IL-6 play a considerable role in the pathogenesis of neuropathy." (PMID 40703750, 2025). "Furthermore, TNFα expression levels correlated positively with the severity of the neuropathy and were particularly elevated in the presence of severe pain in patients with inflammatory PNP." (PMID 37175520, 2023). "Besides TNF-α, IL-6 (interleukin-6) production undergoes an increase in diabetic patients with neuropathy." (PMID 37629665, 2023). "In addition, this recovery mechanism was also confirmed by the analyses of the inflammatory markers mainly involved in neuropathy, such as TNFα and IL-2." (PMID 36982577, 2023). "An experimental study conducted on streptozotocin-induced diabetic rats revealed a close association between the elevation of inflammatory cytokines in brain tissues, such as interleukin-6 and tumor necrosis factor alpha, and the initiation and progression of neuropathy." (PMID 38370902, 2023).